IL22 (interleukin 22)
Diseases named in the same sentence as IL22 in open-access papers (continued):
Sharing a sentence is not in itself a finding about the gene and the disease.
autoimmune disease (continued). "Additionally, Th17 cells (IL-17A, IL-17F, IL-21, and IL-22) are known to play an inflammatory role in mediating autoimmune diseases.." (PMID 38685091, 2024). "Studies have shown that irAEs caused by ICIs have a pathogenesis similar to that of autoimmune disorders, and hyperreactivity of Th17 cells and proinflammatory cytokines such as IL-17A, IL-21 and IL-22 have prominent roles in the pathogenesis of many autoimmune diseases." (PMID 36793048, 2023). "CRCJ may inhibit Th17 cells, which can secrete IL-17 and IL-22, and which play an essential role in autoimmune diseases and body defense responses." (PMID 36248435, 2022). "Particularly, exercise training induced a tendency to decrease all cytokines, with someone reaching significance, including the proinflammatory IL8 and both IL21 and IL22 produced by Th17 cells, which play a critical role in the pathogenesis of autoimmune diseases." (PMID 34853628, 2021). "Up to 8-fold higher levels of IL-17A and 5-fold higher levels of IL-22 are seen in the serum of patients with autoimmune diseases such as rheumatoid arthritis, while a 3-fold increase in serum levels of IL-23 has been reported in patients with multiple sclerosis." (PMID 34203644, 2021). "Here, the roles of Th22/IL-22 in the pathogenesis of autoimmune diseases are reviewed." (PMID 34295334, 2021). "IL-22 is required for the pathogenesis and development of many autoimmune diseases." (PMID 34975883, 2021). "Preclinical studies indicate that IL-22 may serve as a promising therapeutic target for treating autoimmune diseases." (PMID 34295334, 2021). "Therefore, placental explants were treated with a clinically relevant combination of IL-17A, IL-22, and IL-23, at concentrations seen in patients with autoimmune diseases." (PMID 34203644, 2021). "Thus, it seems when cells are already polarized towards Th17 as in the autoimmune diseases, CS enhances IL-17 and IL-22 secretion, but in infectious disease models where IL-22 needs to be induced, CS suppresses the production of IL-22." (PMID 32189996, 2020). "However, it must be recognized that IL‐22 has a dual nature and further studies are needed to determine the precise cellular sources of IL‐22 in different phases of autoimmune diseases." (PMID 31342670, 2020). "In addition, accumulating evidence suggests that IL-22 plays an important role in the pathogenesis of autoimmune diseases." (PMID 30984205, 2019). "ILC3s have been associated with several autoimmune diseases, including inflammatory bowel disease, multiple sclerosis, psoriatic arthritis, and ankylosing spondylitis, either by direct evidence or by involvement of the IL17/IL22 axis." (PMID 30761149, 2019). "Salivary levels of IL-22 show a significant correlation with clinical parameters of Sjögren’s disease, indicating a critical role for this cytokine in the pathogenesis of this autoimmune disease that targets salivary glands." (PMID 29621276, 2018). "Influencing this regulation may be an interesting possibility for the inhibition of IL-22’s harmful action in several autoimmune diseases." (PMID 29572462, 2018). "In addition to infectious diseases, IL-17 and IL-22 also seem to play an important role in autoimmune diseases." (PMID 30402605, 2017). "IL-22 plays a main role in the formation of TLOs in autoimmune diseases." (PMID 28751644, 2017). "IL-22 is an important cytokine in the regulation of tissue and cell responses during inflammation, and it plays a critical role in tissue or cell damage and repair of various autoimmune diseases, chronic inflammatory diseases, infectious diseases and cancers." (PMID 28030850, 2017). "Interleukin (IL)-22+CD4+T (Th22) cells play crucial roles in the pathogenesis of autoimmune diseases and infectious diseases, although the role of Th22 cells remains largely unclear in children with hand, foot, and mouth disease (HFMD) caused by enterovirus 71 (EV71)." (PMID 28030850, 2017).
autoimmune disease (continued). "This T helper subset, by producing pro-inflammatory cytokines such as IL-22 and tumor necrosis factor-α (TNF-α), is implicated in the pathogenesis of autoimmune disease including RA, SLE, Behçet’s disease, type 1 diabetes, immune thrombocytopenia, psoriasis and MS." (PMID 27651750, 2016). "IL-22 is a key effector molecule that plays a critical role in autoimmune diseases." (PMID 26330334, 2015). "IL-22 is secreted by Th17 cells and is highly present in various autoimmune diseases, but whether IL-22 is mediating the inflammation itself, or is a byproduct of the inflammation is depending on the tissue and overall cytokine setting." (PMID 25883945, 2015). "IL-22 expression was involved in several human inflammatory conditions and autoimmune diseases." (PMID 25297677, 2014). "Therefore, Th17 cells tend to secret IL-22 and develop into IL-22 producing Th17 cells in the local immune environment of chronic inflammatory diseases and autoimmune diseases." (PMID 24312440, 2013). "So, diverse pathogenic mechanisms and tissue microenvironments may result in different contributions of IL-22 in autoimmune disease development." (PMID 22485125, 2012). "Apart from IL-22’s dual role in autoimmune disease, what degree of under-expression of IL-22 is detrimental for the eye is currently unknown." (PMID 22312190, 2012). "Additionally, the increased levels of proteins such as IL16, IL22 and SNCA in male MRL mice upon BaP exposure may be a molecular link to the increased risk in end organ damage in subsets of autoimmune disease patients." (PMID 41155532, 2025). "Our results provide novel insights on the role of CD28 and associated signaling mediators in IL-22 regulation in human CD4+ T cells and may provide the biological bases for the development of new therapeutic strategies to dampen inflammatory and autoimmune disorders." (PMID 33178223, 2020). "Moreover, an excessive production of IL-22 together with other cytokines of the Th17 signature has also been involved in maintaining and amplifying the chronic state of several inflammatory and autoimmune diseases." (PMID 33178223, 2020). "However, we now know that ILC3s, though fewer in number, are prolific producers of IL-17 and/or IL-22, as well as other important lung cytokines such as GM-CSF, and thus have the capacity to drive inflammation or repair in a number of infectious and autoimmune diseases." (PMID 30761149, 2019). "Thus, it seams clear that Th17 cells have to produce further factors that, at least in the murine model, cause several autoimmune diseases; IL-17 is only partially responsible while IL-22 is not responsible for this effect." (PMID 30402605, 2017). "Thus, IL-22 plays not only an inflammatory role but also a protective role in autoimmune diseases." (PMID 24040208, 2013). "These effector TH17 cells produce predominantly IL-17, IL-21, and IL-22 plus factors like nitric oxide, matrix metalloproteinase, and prostaglandin E2, each of which is shown to play an important role in the immunopathophysiology of several autoimmune diseases, including SjS." (PMID 19032782, 2008). "In autoimmune diseases, MAIT cells can maintain the integrity of the intestinal epithelial barrier by secreting interleukin (IL)‐22 and can also transform into a major source of the proinflammatory factor IL‐17A under pathological conditions." (PMID 41179703, 2025). "Firstly, we detected IL-2, IL-4, IL-5, IL-13, IL-17A, IL-17F, IL-22, IFN-γ, and TNF-α in the plasma to exclude the influence of infection or autoimmune disorders, and the standard curves were verified." (PMID 38343544, 2024). "T helper 17 (Th17) cells, a novel subset of CD4+ T cells, are known to secrete IL-17A, IL-17F, IL-22, GM-CSF, and IFN-γ, which are involved in inflammation, autoimmune diseases, and graft-versus-host disease (GVHD)." (PMID 37063881, 2023).
autoimmune disease (continued). "The main function of Th17 cells is to produce various cytokines, such as IL-17, IL-21 and IL-22, which stimulate epithelial cells, fibroblasts and smooth muscle cells of the airway to secrete CXCL1 and CXCL8, thereby participating in autoimmune diseases." (PMID 34863307, 2021). "Dysregulation of IL-22 production has also frequently been observed in acute respiratory distress syndrome (ARDS) and several chronic inflammatory and autoimmune diseases." (PMID 33178223, 2020). "Additionally, during the onset of autoimmune disease, TH17 cells signal newly differentiated B cells with IL-22 and IL-23 to regulate glycosyltransferase expression, resulting in a pro-inflammatory agalactosylated, non-fucosylated IgG N-glycan." (PMID 35990620, 2022). "Th17 cells, a key player in autoimmune diseases and antibiosis, are differentiated from naïve T cells (CD4+) stimulated by IL-6, TGF-β, IL-1β, IL-21 and IL-23 and release IL-17A, IL-17F, IL-21 and IL-22." (PMID 28899359, 2017). "In cancers and autoimmune disorders, IL-22 expression is various, with IL-17 as siblings but not twins regarding their biological characteristics." (PMID 26134277, 2015). "These cells produce IL-22, but not IL-17, which is upregulated in patients with autoimmune diseases including systemic lupus erythematosus (SLE), multiple sclerosis (MS), rheumatoid arthritis (RA), and Sjögren's syndrome." (PMID 24527450, 2014). "But importantly, IL-1β and IL-6, both found to be increased in VERA patients, are known to promote the differentiation of Th17 cells, which in turn secrete IL-17A and IL-22, two cytokines that were elevated in VERA patients and have an essential function in the pathogenesis of autoimmune diseases." (PMID 20961415, 2010). "Being involved in responses against extracellular bacterial and fungal infections, autoimmune diseases including encephalomyelitis, but also tumor immunology, TH17 cells have been described as expressors of transcription factor RORyt and producers of IL-17, IL-21, and/or IL-22." (PMID 28290225, 2017). "The situation of IL-22 was not completely consistent in autoimmune diseases." (PMID 22485125, 2012). "The Th17 cell is newly characterized by secretion of IL-17, IL-22, and IL-21 with or without IFN-γ, and its function is opposite to that of the Treg cell in autoimmune disease since Th17 cells usually promote inflammatory processes." (PMID 20064222, 2010).
asthma (92 papers, 2008 to 2026). "Patients with severe T2low asthma, frequently associated with neutrophilic and Th17 inflammation (mainly involving IL-17 and IL-22), have currently limited therapeutic options." (PMID 40082266, 2025). "Asthma was associated with the increased expression of pro-inflammatory cytokines, including IL-2, IL-5, IL-13, IL-17A, IL-22, IL-33, and TNF-α, and reduced levels of anti-inflammatory cytokine, IL-10 and adipokine, leptin in the circulation." (PMID 39902293, 2024). "Further innate inflammatory pathways involving ILC-3s expressing IL-17 and IL-22 have been also described in obesity-associated asthma." (PMID 37761964, 2023). "We found a decrease in the frequency and in the number of CD11c+CD11b+ DC, which is the DC subset that orchestrates Th2 immune response in asthma, in the lungs of IL-22 deficient mice exposed to OVA compared to the WT OVA group." (PMID 37445595, 2023). "As they are tightly linked to asthma immunobiology, and especially to severe asthma, IL-17 and IL-22 appear as promising targets in the treatment of severe asthma." (PMID 35386663, 2022). "Th17 cells have been implicated in non-T2 asthma pathology via the production of IL-17A, IL-17E, and IL-22." (PMID 35454142, 2022). "IL-22 produced by ILC3 is also associated with asthma pathogenesis due to the elevated levels of IL-22 in asthmatic patients compared to healthy controls." (PMID 35413831, 2022). "Several cells and mediators have been linked to T2-low asthma, including the activation of Th1 and Th17, neutrophil infiltration, and cytokines IL-8, IL-17, IL-21, and IL-22." (PMID 33513844, 2021). "RORγt is a transcription factor that enables elaboration of Th17-associated cytokines (including IL-17 and IL-22) and is proposed as a pharmacological target for severe asthma." (PMID 34022896, 2021). "IL‐22 enhanced the expression of the EMT‐associated transcription factors in primary bronchial epithelial cells from patients with severe asthma." (PMID 31725949, 2020). "IL-22 production by ILC3s has also been implicated in asthma pathogenesis, as asthma patients have increased levels of IL-22 compared to healthy controls." (PMID 31134050, 2019). "Recent evidence indicates that Th2 cytokines (such as IL-5 and IL-13) and other T-cell associated cytokines (such as IL-22 and IL-17A) are involved in allergic airway inflammation in asthma." (PMID 29922162, 2018). "In humans, increase in IL-22 has been associated with more severe asthma, and IL-22 enhances human airway smooth muscle cell hyperplasia, epithelial-mesenchymal transition in asthmatic bronchial epithelial cells, as well as cutaneous remodeling." (PMID 25860963, 2015). "While Th2 cytokines are involved in milder forms of allergic asthma, Th17 cytokines (IL-17A, IL-17 F and IL-22) are more strongly associated with severe, difficult to treat asthma." (PMID 24283210, 2013). "IL-22: IL-22, another critical cytokine from Th17 cells, plays a significant role in epithelial barrier dysfunction and mucus hyperproduction, which manifest as hallmark asthma symptoms like wheezing, coughing, and mucus obstruction." (PMID 40564060, 2025). "Consistent with our findings, high expression of IL-22 has also been reported in asthma models in other studies, which may be associated with the repair of the intestinal barrier." (PMID 41561024, 2025). "Additionally, Th17 pathways, ILC3 that expresses both IL-17 and IL-22, and IL-6 have been associated with obesity-related asthma." (PMID 36078171, 2022). "Interestingly, the features of asthma in this model of chronic exposure to aspergillus were reduced by Dectin-1 deficiency which also downregulated IL-17 and IL-22 production." (PMID 35386663, 2022). "However, the role of IL-22 as a protective or a pathogenic actor in asthma remains less clear than that of IL-17, as pathogenic effect failed to be constantly reproduced in murine models." (PMID 35386663, 2022).
asthma (continued). "This may explain the lack of clinical efficacy with anti-IL-17 and IL-17 receptor approaches in severe asthma and that perhaps a broader approach is required to block additional Th17-associated cytokines such IL-22 and IL-26." (PMID 34022896, 2021). "IL-22 production is elevated in allergen-challenged mice and associated with airway hyper-responsiveness, and increased IL-22 expression has also been detected in the serum of asthma patients." (PMID 31354734, 2019). "We therefore hypothesized that intraepithelial neutrophils, together with elevated IL-17A and IL-22, would be associated with worse asthma severity." (PMID 27746241, 2017). "Increased IL-17 and IL-22 productions have been associated with asthma." (PMID 25860963, 2015). "However, there is currently limited information on the role of Th17 associated cytokines, including IL-22, in human asthma." (PMID 24283210, 2013). "There are biomarkers useful for various phenotypes of non-eosinophilic and T2 low asthma; Th17 cells may be responsible for associated with a severe asthma phenotype, which is characterized by neutrophilic inflammation and interleukins such as IL-17A, IL-17F, IL-21 and IL-22." (PMID 40980110, 2023). "The remaining three IL-22 activators were all candidate genes for asthma alone: GNA15, SESN1, and GATA3, of which only GATA3 has been previously reported to directly activate IL-22 in ILC3s113." (PMID 41573945, 2026). "Following their differentiation, Th17 cells release various cytokines, notably IL-17A, IL-17F, IL-22, and IL-21, with IL-17A being the most extensively studied in the context of asthma pathogenesis." (PMID 40564060, 2025). "T2-low asthma, on the other hand, is defined by the absence of T2-high features and can be further classified as either type 17 (T17)-high asthma, marked by neutrophilic inflammation and high circulating levels of IL-17 and IL-22, or T2-low and T17-low asthma." (PMID 40355861, 2025). "Several studies also showed that concurrent increased expression of IL-17 and IL-22 in mononuclear cells and bronchial biopsies correlated with more severe asthma that was resistant to steroids." (PMID 40627451, 2025). "In the DOG-induced model of asthma, airway inflammation is mainly driven by Th17 cytokines (IL-17A and IL-22)." (PMID 40082266, 2025). "T2-low inflammatory endotype: T2-low asthma has no T2-high biomarkers and can be separated into T17-high asthma (neutrophilic airway inflammation, and high IL-17 and IL-22 levels) and T2-low/T17-low asthma." (PMID 40486460, 2025). "In severe asthma, where neutrophils are dominant, T-helper 17 (Th 17) cells secrete IL-17 A, IL-17 F, IL-21, IL-22, and TNF-α which drive inflammation and airway hyperresponsiveness." (PMID 40605076, 2025). "For example, a cross‐sectional study of asthmatic patients with highly neutrophilic asthma identified high levels of IL‐17+ and IL‐22+ staining cells in the bronchial lamina propria compared to patients without neutrophilic asthma." (PMID 39073027, 2024). "Next, the levels of IL-2 and IL-22 showed a significant increase only in asthma groups (NW-A and OO-A) compared to the NW group." (PMID 39902293, 2024). "Several studies agree that IL-22 can attenuate allergic airway inflammation in an ovalbumin-induced asthma mouse model." (PMID 39687635, 2024). "We have previously reported that an IL‐22/Th22 signalling pathway gene signature was raised in patients with severe neutrophilic and mixed granulocytic asthma." (PMID 39073027, 2024). "The children with asthma had an inflammatory profile that was characterized by increased levels of several pro-inflammatory cytokines, including IL-2, IL-5, IL-13, IL-17A, IL-22, IL-33, TNF-α, and reduced level of anti-inflammatory cytokine, IL-10." (PMID 39902293, 2024). "RORγt blockade in a Th2 low mouse model of asthma suppressed both IL‐17 and IL‐22 expression and attenuated AHR and neutrophilia." (PMID 39073027, 2024).